IFNG (interferon gamma)
Diseases named in the same sentence as IFNG in open-access papers (continued):
Sharing a sentence is not in itself a finding about the gene and the disease.
tumor (continued). "Subclustering and GSEA in non-malignant cell clusters revealed similar tumor-wide changes in transcriptional phenotype, with increased IFNα, IFNγ, inflammatory response and IL2-Stat5 signaling again observed as well as decreases in oxidative phosphorylation." (PMID 38286828, 2024). "Interestingly, the antitumor effect of combination Ad-E and αPD-1 mAb treatment in mice was restored to some extent after oral gavage Bacteroides fragilis by increasing the accumulation of tumor-infiltrating CD3+ T cells, NK cells, IFNγ+CD8+ T cells." (PMID 39251538, 2024). "When examining the phenotype of CD27+Ly6C− and CD27+Ly6C+ γδ T cells in KP and KB1P tumor-bearing mice, we found that CD27+Ly6C+ γδ T cells expressed higher levels of CD160, NKG2A, IFNγ, and CD44 in spleen, LN, and lung, analogous to observations made in tumor-naive mice." (PMID 38816652, 2024). "However, a significantly higher percentage of interferon-gamma (IFN-γ) producing and a lower percentage of interleukin-10 (IL-10) producing CD4+ T cells derived from the spleen of tumor-bearing A. vulgaris extract treated mice were found." (PMID 38920557, 2024). "Additionally, lymphocytes secrete cytokines such as interferon-gamma (IFN-γ and tumor necrosis factor-alpha (TNF-α which enhance the anti-tumor activity of other immune cells." (PMID 39170737, 2024). "We found that STAT1-Y701 phosphorylation was obviously decreased in IFNγ-stimulated HCC cells with HKDC1 knockdown compared to that in stimulated NTC controls, as well as in YAP5SA-induced HCC-bearing HKDC1 KO mice relative to tumor-bearing WT mice." (PMID 38351096, 2024). "Besides IFNγ production, we also analyzed the presence of antigen-specific CD8+ T cells by staining with MHC dextramers containing tumor antigen peptides in HLA-A1, HLA-A2, or HLA-B35 positive patients." (PMID 38395969, 2024). "In addition, stroma-restricted CD8/CD4 T cells supply IFNγ and TNF/IL1 to the tumor nest, which further promotes tumor NOS2/COX2 expression at the tumor margin that leads to the formation of metastatic and CSC niches that are regionally distinct." (PMID 39356141, 2024). "SIRPA blockade also rescued the numbers of CD8+ T cells and NKP46+ NK cells in tumour-bearing livers of Clec4fcreId3f/f mice, the formation of the peritumoural CD8+ T cell and NKP46+ NK-rich zone and the production of IFNγ and TNF by CD8+ T cells and NK cells." (PMID 38326607, 2024). "Specifically, IFNγ activates macrophages and microglia, recruits and stimulates cytotoxic T cells, polarises CD4+ T cells into Th1 effector cells, and inhibits tumour-promoting regulatory T cells (Tregs)." (PMID 39596267, 2024). "Additionally, in the ambiance of HPV+ tumor cells, CD4+T cells exhibit enhanced IFNγ secretion, which is critical to orchestrating adaptive immune response against viral and tumoral antigens." (PMID 39105803, 2024). "More strikingly, when they enter TIME, they are reprogrammed into IFNγ-producing cells promoting tumor clearance without autoimmune abnormalities." (PMID 39227959, 2024). "Tumor Treg depletion by IL‐2‐Fc was most evident in our early time point monotherapy studies, especially 1 day posttreatment in our MC38/CEA short term study, with some mice reaching a >50‐fold higher IFNγ+CD8+/Treg ratio." (PMID 38317590, 2024). "Another group has explored the immunogenicity of non-canonical HLA-I tumor antigens identified through proteogenomics and shown that at least some of them are immunogenic (IFNg production and upregulation of 4-1BB) and shared across patients." (PMID 38920720, 2024). "Moreover, although NK and CD8+ T cells recruited to liver tumours of wild-type mice produce IFNγ and TNF, the production of IFNγ and TNF was reduced in the remaining NK and CD8+ T cells present in the liver of tumour-bearing Clec4fcreId3f/f mice." (PMID 38326607, 2024). "Reciprocally, HPV+ tumor cells could directly interact with CD4+T cells and activate CD4_C3_CXCL13 T cell differentiation, which also had elevated secretion of IFNγ." (PMID 39105803, 2024).
tumor (continued). "Local activation of the IFNγ/CXCL9 axis, with no detectable increase in IFNγ within the lymphatic system, results in an immunologically hot (inflamed) tumor, but with minimal impact outside of the TME." (PMID 38698860, 2024). "It has been suggested that modifications in the tumor microenvironment, such as increased levels of TNF-α, interferon-gamma, T cell infiltration, and reduced levels of interleukin-6 and interleukin-8, could be associated with irAEs and treatment outcomes." (PMID 39717410, 2024). "Therefore, the proportion of immune cells including CD4+, CD8+ T cells, and NK cells, the major IFNγ producers, were analyzed in the B16F10 tumor model at the early stage (1, 3, 5, 7d) post ablation." (PMID 38827732, 2024). "Furthermore, the injection of LNCs@CSF1R siRNA increased the production of effector cytokines IFNγ and GzmB by CD8 + T cells within the tumor." (PMID 38992688, 2024). "Additionally, the use of PDT and TLR5 agonist flagellin has been shown to stimulate the infiltration of tumor CD8+ T cells and the secretion of Interferon-gamma (IFN-γ) throughout the entire organism." (PMID 38481994, 2024). "Interestingly, research has also found NK cells can reduce their IFNγ production via up-regulation of CTLA4, which is accompanied by tumor development, thereby promoting tumor progression." (PMID 38244071, 2024). "Furthermore, various cytokines secreted by lymphocytes, including interferon-gamma (IFN-γ) and tumor necrosis factor-alpha (TNF-α), contribute to tumor suppression and extend the survival of cancer patients." (PMID 39654896, 2024). "Because effector CD8+ T cells secreted IFNγ and TNF to regulate anti-tumor immunity and gene expression in tumor cells, we speculated that TNF and IFNγ secreted by activated CD8+ T cells may induce PRMT3 expression in HCC." (PMID 39256398, 2024). "Also, immunofluorescence (IF) and flow cytometry analyses revealed that PRMT3 inhibition led to a robust increase in the abundance of tumor-infiltrating CD4+ and CD8+ T cells, including IFNγ + CD8+ and GZMB+ CD8+ T cells." (PMID 39256398, 2024). "Nevertheless, despite the lack of response, the levels of Ly6Ehi neutrophils in the tumor were significantly elevated by IFNγ/α treatment, reinforcing the fact that IFN induces Ly6Ehi neutrophils both in vivo and in vitro (respectively)." (PMID 38181798, 2024). "Finally, we demonstrated that interferon-gamma (IFN-γ), which is known to induce IFITM1 expression, suppressed tumor progression in xenograft mice injected with MPNST cells." (PMID 39273214, 2024). "However, when HER2-CAR-T cells and PD-1 blockade were combined, more interleukin-2 (IL-2) and interferon-gamma (IFN-γ) were released, which led to greater tumor elimination." (PMID 38486856, 2024). "CD8+ T cells and NK cells are capable of directly identifying and eliminating tumors, while CD4+ T cells contribute indirectly by producing cytokines like interferon-gamma(IFN-γ) and tumor necrosis factor-alpha(TNF-a), thus participating in anti-tumor immune responses." (PMID 38914941, 2024). "However, in advanced diseases, ILC1s are found to demonstrate an exhausted phenotype in the tumour microenvironment (TME) with impaired effector functions, characterised by decreased responsiveness to cytokines and reduced IFNγ production." (PMID 38745765, 2024). "Interestingly, in the Sb9 KO tumors in Sb9 KO mice, there are increased ratios of CD8+, CD44+CD62L-CD8+, TNFα+CD8+, GzmB+CD8+, and IFNγ+CD8+, as compared with those from the WT tumor in WT mice." (PMID 38966643, 2024). "It has been found that the M1 phenotype is acquired after being stimulated with pro-inflammatory factors, such as Toll-like receptor 4 (TLR-4) ligands and interferon-gamma (IFN-γ), and then eliminates tumor cells by producing inflammatory factors (e.g., TNF-a)." (PMID 39061427, 2024).
tumor (continued). "Macrophages can be activated by interferon gamma (IFNγ) and Toll-like receptor (TLR) agonists to develop an inflammatory (M1-like) phenotype, thus exhibiting proinflammatory characteristics with microbial killing and tumor growth inhibition." (PMID 38650937, 2024). "As a part of the viral immune response, T cells would provoke extensive expression of cytokines including IFNγ, which might sequentially promote the tsMHC-II expression in HPV+ tumor cells." (PMID 39105803, 2024). "Blocking AR signaling can sensitize the tumor-bearing host to effective checkpoint blockade by directly enhancing CD8 T cell function, preventing T cell exhaustion, and improving responsiveness to PD-1 targeted therapy via increased IFNγ expression." (PMID 38698844, 2024). "It is not clear why more IFNγ producing T cells accumulate in tumours formed in Dock2 mutant mice, a gene that is expressed primarily in hematopoietic cells." (PMID 39242821, 2024). "In addition to their endogenous anti-tumor role, CD27+ IFNγ-producing γδ T cells control tumor growth after ex vivo expansion and adoptive cell transfer into tumor-bearing mice, mirroring the outcomes of experiments using human Vγ9Vδ2+ or Vδ1+ cells." (PMID 38816652, 2024). "During the tumor formation in B16F10 cell-challenged C57BL/6 mice, serum levels of several cytokines were monitored using ELISA to evaluate the effect of Hcs treatment: IL4, IL10, and IFNγ." (PMID 38786612, 2024). "Relying on the secretion of interferon-gamma (IFNγ), we repeatedly observed increased major histocompatibility complex (MHC)-dependent tumor reactivity of CB CD8+ T cells versus paired samples from tumor or peripheral blood." (PMID 39085419, 2024). "Besides, FACS analysis of subcutaneous tumors revealed that SRC‐1 knockout combined with PD‐L1 antibody therapy also increased the effector function of tumor‐infiltrating CD8+ T cells, as reflected in the up‐regulation of IFNγ+CD8+ T cells proportion." (PMID 38953362, 2024). "Indeed, the expression of CCL5, IFNG, CXCL9 and CXCL10 positively correlated among themselves as well as with the numbers of tumor-infiltrating NK cells in the original biopsy." (PMID 38167224, 2024). "While our in vitro studies indicate that EZH2 inhibition and IFNγ are both required for MHCII upregulation, in vivo the changes seen in the tumor cells may be secondary to immune modulation by EZH2 inhibition." (PMID 38265267, 2024). "Tumor-derived GLI1 sustains expansion and invasion of PMN-MDSCs in vitro, and promotes their immunosuppressive activity on T cells, inhibiting their effector capability, as demonstrated by the reduced production of IFNγ by CD4 + and CD8 + T cells." (PMID 39090759, 2024). "TIGIT blockade during co-culture with A549 spheroids did not mitigate the tumor-induced decrease in IFNγ expression after restimulation with PVR− cells with still only 9 ± 7% of cells expressing IFNγ." (PMID 37345049, 2023). "On the other hand, CTL recognition of a few tumor cells can elicit sufficient IFNγ secretion to cover distances of several hundred micrometers and inhibit tumor growth even in regions not frequented by CTLs." (PMID 37261345, 2023). "The production of high levels of IFNγ can further orchestrate an antitumor milieu and create a feedback loop between IL-12 and IFNγ, increasing expression of major histocompatibility class I and II molecules (MHC-I/MHC-II) and tumor antigen presentation and recognition." (PMID 38260854, 2023). "It will be important to determine whether IFNγ PET can identify intratumoral immune activity in patients treated with ICI, and whether tumor location or size influences imaging efficacy." (PMID 38130991, 2023). "In addition, IFNγ also increases the expression of checkpoint inhibitors, such as indoleamine-2,3-dioxygenase 1 (IDO1) and CTLA-4, leading to enhanced tumor growth." (PMID 37190141, 2023).
tumor (continued). "GSDMB can be induced by interferon gamma (IFN-γ) and tumor necrosis factor alpha (TNF-α), which could be released by tumor-infiltrating CD8 T cells and other immune cells, thus providing a positive feedback loop." (PMID 36742298, 2023). "Therefore, we developed an ODE model to describe tumor growth, CTL infiltration, CTL production of IFNG and subsequent interference with cell-cycle progression, and also tumor cell killing by CTLs." (PMID 37182110, 2023). "TGFβ regulates the production of various cytolytic genes as well, including granzyme A, granzyme B, IFNγ, and FAS ligand, thereby impairing the anti-tumor activity of CD8+ T cells during the adaptive immune response and ultimately resulting in pro-tumorigenic TME." (PMID 38035101, 2023). "The primed and activated effector T cells gradually migrate and infiltrate into the tumor tissues, identify the tumor by specific T cell receptor (TCR) and antigen binding, and then release perforin, granzyme B (GZMB), and interferon-gamma (IFN-γ) to induce killing of tumor cells." (PMID 37397393, 2023). "As in previous trials, immune responding patients with wild-type IDH1 (those exhibiting ≥50% increased IFNγ tumor antigen response post-vaccine without IDH1R132H) showed significantly increased progression-free survival (PFS) after DC vaccination." (PMID 37161052, 2023). "Furthermore, we identified some potential prognostic biomarkers for HCC, a highly malignant tumor with high incidence and mortality rates, including AFP, H2AC19, KLF11, and IFNG." (PMID 37107646, 2023). "Further, MV infection of HT-29 combined with tumor-binding CEAxCD16A vBiKE treatment resulted in higher IFNγ concentrations compared to the non-binding control." (PMID 36765035, 2023). "To confirm this result, we also pre‐cocultured BMDCs with either the control or Arf1‐ablated tumor cells in the presence of OVA and then re‐cocultured the treated BMDCs with naïve CD8+ OT1 T cells, we observed similar increases of the tumor antigen‐specific CD8+ T cells and IFNγ production." (PMID 37786300, 2023). "At the functional level, colonization of these 11 strains could enhance ICI efficacy in the subcutaneous CRC mouse model with increased levels of granzyme B+IFNγ+CD8+ T cells and tumor-infiltrating dendritic cells." (PMID 35914737, 2023). "Thus, because IFNγ is mainly produced by CD8+ T cells and NK cells, this allows for inhibitory feedback from tumor cells." (PMID 37296927, 2023). "Tumor-derived EVs carrying cell death receptors and their ligands can induce apoptosis on T cells by activating caspases 3 and 7; additionally, tumor-derived EVs can decrease the synthesis of TNF-α and Interferon gamma (IFN-γ) via Tc cells in a dose-dependent manner." (PMID 37175226, 2023). "The ability of N803 to induce antitumor effects stems from its ability to induce significant expansion and activation of NK cells and CD8+ central memory T cells in the periphery, as well as IFNγ production and infiltration of CD8 T cells into the tumor microenvironment." (PMID 37371081, 2023). "One study showed that CCR2 blockade by a CCR2 antagonist in vivo decreased the number of M2 macrophages, increased the number of IFNγ + CD8 + T cells, and inhibited tumor growth, indicating that M2 macrophage-mediated indirect effects significantly affect tumor growth." (PMID 37865750, 2023). "Tumour cells surrounding clusters of CD11c-Venus+ immune cells with CD4+ T cells upregulated the expression of MHC-II exclusively in mice bearing HCmel12 CRISPR-ctrl tumours, consistent with the notion that CD4+ T cells were activated locally and secreted IFNγ in an antigen-dependent manner." (PMID 37316667, 2023). "On day 15 of treatment, we observed a significant upregulation of tumour immunogenicity markers (MHCI and PD-L1), significant increase in the proportion of tumour-infiltrating CD8+ and CD4+/FOXP3- T effector cells as well as the production of IFNγ by CD4+ T cells." (PMID 37582853, 2023).
tumor (continued). "Furthermore, IL33 expression levels were positively correlated with those of Th1 cytokines (IL2 and IFNG) and Th2 cytokines (IL4 and IL10) in 41 tumor tissues." (PMID 37056569, 2023). "IFNγ released from T cells is an activator of the ferroptosis regulator ACSL4 and can accelerate the incorporation of AA into phospholipids, subsequently inducing immunogenic tumor ferroptosis." (PMID 37840106, 2023). "We then evaluated the tumor cell killing activity of TAG72-CAR T cells expressing either of the two versions of mbIL12, and found that TAG72-CAR/mbIL12(CD28tm) T cells displayed greater tumor cell killing activity, T-cell expansion, and IFNγ production." (PMID 37550294, 2023). "To verify that whether liver-targeted IFNγ has a similar anti-tumor effect as YB1, we prepared chimeric AAV2/8 specifically targeting the liver as an IFNγ delivery vector." (PMID 38020179, 2023). "This suggested that despite IFNγ being critical for tumor control, this cytokine did not need to act directly on tumor cells to exert an effect." (PMID 36881506, 2023). "MHC-I expression on tumor cells was significantly higherin groups treated with 4-1BBL/IL-12 NPs with or without anti-PD1 aswell as 4-1BBL/IL-12/IFNγ NPs with or without anti-PD1." (PMID 37797944, 2023). "Tumor-infiltrating CD8+ T cells were more activated (as reflected by the proportion of PD-1+TIM-3+ CD8+ T cells) and exhibited enhanced cytotoxicity (as reflected by Granzyme B and IFNγ levels)." (PMID 37500611, 2023). "We documented the emapalumab ability to neutralize high concentration of IFNγ produced by CAR-T cells upon the engagement with tumor cells; we also showed that this neutralization does not affect the antitumor activity of CAR.CD19-T cells." (PMID 37296093, 2023). "IFNγ and ICAM-1 dependent conjugation formation between hHER2-CAR-T cells and target tumor cells was further confirmed by incubating tumor cells with recombinant IFNγ with/without an anti-LFA-1 blocking antibody." (PMID 37388744, 2023). "The expanding DNTs in vivo acquired an anti-tumor phenotype with the NK cell marker NKG2D, DNAM-1, which mediated the cytotoxicity response targeting cancer cells by secreting cytotoxic cytokines such as IFNγ and soluble TRAIL (sTRAIL)." (PMID 37889543, 2023). "In addition, overexpression of DSE promoted the overexpression of tumor killer molecules such as GZMB, TNF and IFNG in CD8 + T cells, and inhibited the expression of inhibitory molecules such as PD-1, TIM-3 and LAG-3." (PMID 37833287, 2023). "Nanoparticles loaded with obeticholic acid were enriched in liver sinusoidal endothelial cells and Kupffer cells and attenuated tumor growth in an orthotopic mouse model, accompanied by increased secretion of CXCL16 and IFNγ and expansion of natural killer T (NKT) cell populations within the tumor." (PMID 37686465, 2023). "Thus, we found that PARP14 pharmacological antagonism or silencing in tumour cells enhanced STAT1 phosphorylation and expression of STAT1 target gene products, including IRF1 responsible for the expression of many IFNγ signalling genes but also PARP14 itself." (PMID 37752135, 2023). "We simulated limited heterogeneity so that no epithelial tumor cells spontaneously underwent EMT in the absence of IFNγ." (PMID 37638024, 2023). "NAMPT was upregulated in C1498 but not in MC38 cells, suggesting tumor type dependency in the IFNγ-induction of NAMPT." (PMID 36900204, 2023). "In addition, interferon gamma (IFN-Ɣ) pathway is known to be involved in PDL1 expression and is a key feature to several anti-tumor immune expression signatures, such as the T cell-inflamed signature (TIS)." (PMID 37726776, 2023). "As increased tumor control occurred without the addition of checkpoint blockade, we conclude that IFNγ sensing by CD8 T cells is an independent pathway restricting T cell anti-tumor immunity." (PMID 36658158, 2023).